RAB5IF (RAB5 interacting factor)
Description:
Component of the multi-pass translocon (MPT) complex that mediates insertion of multi-pass membrane proteins into the lipid bilayer of membranes. The MPT complex takes over after the SEC61 complex: following membrane insertion of the first few transmembrane segments of proteins by the SEC61 complex, the MPT complex occludes the lateral gate of the SEC61 complex to promote insertion of subsequent transmembrane regions. Within the MPT complex, the GEL subcomplex may mediate insertion of transmembrane regions into the membrane. In addition to its role in multi-pass membrane insertion, RAB5IF/OPTI also acts as an assembly factor for mitochondrial respiratory complexes.
Synonyms: RIP5; C20orf24; OPTI; RCAF1; PNAS-11; CFSMR2
Tractability: Antibody: UniProt predicts a signal peptide or a membrane-spanning region. PROTAC: ubiquitination databases record sites on it.
Gene: Protein-coding gene on chromosome 20 (36,605,779 to 36,612,557, forward strand). Ensembl gene ENSG00000101084.
Subcellular location: Endoplasmic reticulum membrane; Mitochondrion inner membrane
Subcellular location (Human Protein Atlas): Mitochondria
Pathways (Reactome):
Metabolism: Complex IV assembly
Gene Ontology:
Molecular function: protein binding
Biological process: mitochondrial respirasome assembly; multi-pass transmembrane protein insertion into ER membrane
Cellular component: mitochondrial inner membrane; mitochondrion; multi-pass translocon complex; endoplasmic reticulum membrane; cytoplasm
Genetic constraint (gnomAD): Loss-of-function variants: 13 observed, 18.07 expected, observed/expected ratio (o/e) 0.72, 90% interval 0.47 to 1.14. The upper end of that interval is the gene's LOEUF score, 1.14, which puts it in group 5 of 6, group 1 being the genes least tolerant of losing a copy. Missense variants: 133 observed, 142.78 expected, observed/expected ratio (o/e) 0.93, 90% interval 0.81 to 1.08. Synonymous variants: 62 observed, 58.62 expected, observed/expected ratio (o/e) 1.06, 90% interval 0.86 to 1.31.
Homologues: Orthologues: guinea pig RAB5IF (98% identical), mouse Rab5if (98% identical), rat Rab5if (98% identical), pig RAB5IF (93% identical), rabbit RAB5IF (91% identical), tropical clawed frog rab5if (74% identical), zebrafish rab5if (72% identical), dog RAB5IF (64% identical), chimpanzee RAB5IF (63% identical), Drosophila melanogaster CG12107 (53% identical), Caenorhabditis elegans F44E7.9 (36% identical).
Diseases named in the same sentence as RAB5IF in open-access papers:
RAB5IF is named in the same sentence as 7 diseases in open-access papers, as found by Europe PMC text mining. Sharing a sentence is not in itself a finding about the gene and the disease. The quoted sentences say what the papers report.
colorectal carcinoma (1 paper, 2019). A malignant epithelial neoplasm that arises from the colon or rectum and invades through the muscularis mucosa into the submucosa. "Interestingly, C20orf24, a gene symbol of RAB5IF, was involved in the progression of colorectal carcinoma cells." (PMID 31717443, 2019). "Furthermore, recent evidence suggests that, C20orf24, a gene symbol of LncRNA RAB5IF, was involved in the progression of colorectal carcinoma cells." (PMID 31717443, 2019).
COVID-19 (1 paper, 2022). A disease caused by infection with severe acute respiratory syndrome coronavirus 2. "Additionally, we found 44, 42, and 53 up-DEGs that were notably associated with mild, moderate, and severe COVID-19, and there were six significant common genes across three phases of COVID-19, including TCF7, GZMH, RAB5IF, CCND2, BIRC6, and NDUFAF3." (PMID 35172892, 2022).
hepatocellular carcinoma (1 paper, 2019). A malignant tumor that arises from hepatocytes. "In the current study, the function of long noncoding RNA (LncRNA) RAB5IF was elucidated in hepatocellular carcinoma (HCCs) in association with LGR5 related signaling." (PMID 31717443, 2019). "Overall, these findings provide novel evidence that LncRNA RAB5IF promotes the growth of hepatocellular carcinoma cells via LGR5 mediated β-catenin and c-Myc signaling as a potent oncogenic target." (PMID 31717443, 2019). "Taken together, these findings for the first time demonstrate novel evidence that LncRNA RAB5IF promotes the growth hepatocellular carcinoma cells via upregulation of LGR5 mediated β-catenin and c-Myc signaling axis as a potent oncogenic target." (PMID 31717443, 2019). "Taken together, these findings for the first time demonstrate novel evidence that LncRNA RAB5IF promotes the growth of hepatocellular carcinoma cells via upregulation of LGR5 mediated β-catenin and c-Myc signaling axis as a potent oncogenic target." (PMID 31717443, 2019).
RAB5IF also shares sentences with these, for which no sentence is quoted: cancer (2 papers); adenoma (1); deficiencies (1); tumor (1).